BNIP1 (BCL2 interacting protein 1)
Description:
As part of a SNARE complex may be involved in endoplasmic reticulum membranes fusion and be required for the maintenance of endoplasmic reticulum organization. Also plays a role in apoptosis. It is for instance required for endoplasmic reticulum stress-induced apoptosis. As a substrate of RNF185 interacting with SQSTM1, might also be involved in mitochondrial autophagy (Probable).
Synonyms: TRG-8; NIP1; SEC20; SEDH
Tractability: Antibody: UniProt predicts a signal peptide or a membrane-spanning region. PROTAC: UniProt records ubiquitination sites on it; ubiquitination databases record sites on it; its protein half-life has been measured.
Gene: Protein-coding gene on chromosome 5 (173,144,442 to 173,164,397, forward strand). Ensembl gene ENSG00000113734.
Subcellular location: Endoplasmic reticulum membrane; Mitochondrion membrane
Subcellular location (Human Protein Atlas): Endoplasmic reticulum
Pathways (Reactome):
Vesicle-mediated transport: COPI-dependent Golgi-to-ER retrograde traffic
Gene Ontology:
Molecular function: calcium-induced calcium release activity; protein binding; SNAP receptor activity
Biological process: apoptotic process; apoptotic process in response to mitochondrial fragmentation; endoplasmic reticulum membrane fusion; endoplasmic reticulum organization; execution phase of apoptosis; negative regulation of apoptotic process; retrograde vesicle-mediated transport, Golgi to endoplasmic reticulum; calcium-mediated signaling; response to activity; response to oxygen-glucose deprivation; response to starvation
Cellular component: cytoplasm; endoplasmic reticulum; endoplasmic reticulum membrane; intracellular membrane-bounded organelle; mitochondrial membrane; mitochondrial outer membrane; nuclear envelope; SNARE complex; COPI-coated vesicle
Genetic constraint (gnomAD): Loss-of-function variants: 23 observed, 26.46 expected, observed/expected ratio (o/e) 0.87, 90% interval 0.62 to 1.23. The upper end of that interval is the gene's LOEUF score, 1.23, which puts it in group 5 of 6, group 1 being the genes least tolerant of losing a copy. Missense variants: 266 observed, 284.24 expected, observed/expected ratio (o/e) 0.94, 90% interval 0.85 to 1.04. Synonymous variants: 118 observed, 105.44 expected, observed/expected ratio (o/e) 1.12, 90% interval 0.96 to 1.3.
Homologues: Orthologues: chimpanzee BNIP1 (100% identical), macaque BNIP1 (99% identical), pig BNIP1 (96% identical), rabbit BNIP1 (96% identical), guinea pig BNIP1 (95% identical), rat Bnip1 (95% identical), mouse Bnip1 (94% identical), tropical clawed frog bnip1 (79% identical), zebrafish bnip1b (75% identical), zebrafish bnip1a (75% identical), dog BNIP1 (71% identical), Drosophila melanogaster Sec20 (34% identical), and 1 more.
Diseases named in the same sentence as BNIP1 in open-access papers:
BNIP1 is named in the same sentence as 6 diseases in open-access papers, as found by Europe PMC text mining. Sharing a sentence is not in itself a finding about the gene and the disease. The quoted sentences say what the papers report.
breast carcinoma (1 paper, 2019). "With the web resource of UALCAN, the mRNA expression of BNIP1 (p = 0.048) and BCLAF1 (p = 0.00014) displayed a significantly negative correlation with breast cancer patients’ overall survival." (PMID 30678233, 2019).
cardioembolic stroke (1 paper, 2019). "CAV1, SURF1, PLEKHH2, ECD, BNIP1, CAV2 are found to be associated with cardioembolic stroke and Small vessel stroke in Europeans." (PMID 32038707, 2019).
cervical cancer (1 paper, 2021). A primary or metastatic malignant neoplasm involving the cervix. "It was reported that BNIP1 could restrain cervical cancer cell proliferation, migration and invasion by inhibit mTOR signaling pathway, although it seemed to be a risky factor in UM patients." (PMID 33682883, 2021).
infection (2 papers, 2017 to 2021). The state of being infected such as from the introduction of a foreign agent such as serum, vaccine, antigenic substance or organism. "Strikingly, infection of wild-type but not ΔdotA L. pneumophila promoted the association of 3x-FLAG-Rab6A with Stx18, p31, and BNIP1." (PMID 33760868, 2021).
BNIP1 also shares sentences with these, for which no sentence is quoted: small vessel stroke (1 paper); tumor (1).